EZH2 (enhancer of zeste 2 polycomb repressive complex 2 subunit)
Diseases named in the same sentence as EZH2 in open-access papers (continued):
Sharing a sentence is not in itself a finding about the gene and the disease.
liver fibrosis (continued). "Taken together, these experiments and ours confirm the coordinated involvement of active (ASH1 H3K4 methylation) and repressive (EZH2 H3K27 methylation) epigenetic marks in progression and resolution of liver fibrosis." (PMID 25380300, 2014). "Moreover, EZH2-mediated inhibition of KLF14 expression via H3K27me3 promoted hepatic stellate cell activation and liver fibrosis." (PMID 35264108, 2022). "Furthermore, in vivo administration of EPZ‐6438, a specific inhibitor for EZH2, dramatically alleviated TAA‐established liver fibrosis in rats." (PMID 34031939, 2021). "The expression pattern of EZH2 and JMJD3 during HSCs activation and liver fibrosis progression indicates that they might be involved in HSCs biology and have pathological relevance." (PMID 33391480, 2021). "EPZ‐6438, a specific EZH2 inhibitor, dramatically ameliorated TAA‐induced rat hepatic fibrosis." (PMID 34031939, 2021). "The EZH2 inhibitor EPZ‐6438 rescues EZH2‐mediated KLF14 downregulation, which transactivates PPARγ expression, converts the activated HSCs to the quiescent phenotype and induces apoptosis, and therefore alleviating liver fibrosis." (PMID 34031939, 2021). "Significant differences in the regulation of liver fibrosis and HCC-related genes by Ezh1/Ezh2 are seen in male compared to female liver, which may contribute to the sex bias in liver disease progression." (PMID 32428001, 2020). "In addition, we show that EZH2 inhibition attenuates HSC activation in vitro and liver fibrosis in vivo." (PMID 30539787, 2019). "Additionally, we investigated the role of ASH1 and EZH2 methyltransferases in mMMP-9 and HGF gene therapy-induced resolution of CCl4-model of rat liver fibrosis." (PMID 25380300, 2014). "Additionally, another anti-fibrotic gene repressed by EZH2 is peroxisome proliferator-activated receptor gamma (PPAR-γ), a ligand-activated transcription factor that promotes protective effects against including liver fibrosis." (PMID 39408226, 2024). "Moreover, ectopic expression of KLF14 or inhibition of EZH2 with EPZ-6438 treatment could restore PPARγ expression and alleviate fibrosis in a rat thioacetamide liver fibrosis model." (PMID 37476157, 2023). "Thirdly, there might exist other genes also critical for anti‐fibrosis, and these genes were transrepressed by EZH2, in this sense, EPZ‐6438 administration might result in transactivation of these anti‐fibrotic genes, and therefore alleviating liver fibrosis (the unknown way)." (PMID 34031939, 2021). "Thus, Ezh1/Ezh2-catalyzed H3K27-trimethyation regulates sex-dependent genetic programs in liver metabolism and liver fibrosis through its sex-dependent effects on the epigenome, and may thereby determine the sex-bias in liver disease susceptibility." (PMID 32428001, 2020). "Then, they showed that RA and BC suppressed the expression of EZH2 methyltransferase with consequent reduction of PPARγ H3K27di-methylation which resulted in the formation of euchromatin and increased transcription of PPARγ leading to inhibition of HSC activation and progression of liver fibrosis." (PMID 25380300, 2014).
esophageal squamous cell carcinoma (33 papers, 2012 to 2025). Esophageal squamous cell carcinoma (ESCC) is a type of esophageal carcinoma (EC) that can affect any part of the esophagus, but is usually located in the upper or middle third. "A comparable association was observed between EZH2 expression and esophageal SCC chemoradiotherapy response." (PMID 40135141, 2024). "And it has been confirmed in several researches that SNHG6 inhibited apoptosis by regulating EZH2 expression via the sponging of MiR-101-3p in esophageal squamous-cell carcinoma." (PMID 37626362, 2023). "For instance, CASC9 promoted esophageal squamous cell carcinoma (ESCC) progression by negatively regulating PDCD4 expression through recruiting EZH2." (PMID 36494339, 2022). "For example, lncRNA HERES regulates canonical and non-canonical Wnt signaling pathways through interacting with EZH2 in esophageal squamous cell carcinoma." (PMID 33511127, 2020). "The enhancer of zeste homolog 2 (EZH2) was found to be overexpressed and associated with tumor metastasis in esophageal squamous cell carcinoma (ESCC)." (PMID 22867052, 2012). "lncRNA Xist involves esophageal squamous cell carcinoma development via regulation of miR-101/EZH2 axis, and facilitates esophageal squamous cell carcinoma proliferation, apoptosis, migration, and invasion via regulation miR-494/CDK6 axis and activation of JAK2/STAT3 signal pathway." (PMID 34178980, 2021). "Similar observations were collected in esophagus squamous cell carcinoma, in which EZH2 expression levels are higher in tumors compared to adjacent tissues and this higher expression has been correlated to the apparition of distant metastasis, bad prognosis, depth of invasion, and tumor size." (PMID 34991274, 2018). "For instance, LncRNA SNHG6 downregulates the miR-101-3p/EZH2 pathway in esophageal squamous cell carcinoma (ESCC), and circNTRK2 promotes cell proliferation, migration, and EMT by sponging miR-140-3p and upregulating NRIP1." (PMID 39944625, 2025). "The lncRNA taurine upregulated gene 1 (TUG1) (NCBI GeneID: 55000) was also demonstrated to suppress PDCD4 by recruiting EZH2 in esophageal squamous cell carcinoma (ESCC) through epigenetic modification." (PMID 31620370, 2019). "In esophageal squamous cell carcinoma (ESCC), SOX4 cooperates with EZH2 and HDAC3 to enhance tumor cell progression and metastasis through epigenetic silencing of miR-31 by H3K27me." (PMID 38331879, 2024). "In this study, we have evaluated the effect of the EZH2 gene on miR-200c and EMT genes in esophageal squamous cell carcinoma." (PMID 36316365, 2022). "In this study, the effect of EZH2 expression on miR-200c and important genes of the EMT pathway was investigated in esophageal squamous cell carcinoma (ESCC)." (PMID 36316365, 2022). "In the esophageal squamous cell carcinoma cell line, Ecal09, miR-98, and miR-214 also targeted the 3’-UTR of EZH2 mRNA and inhibited migration and invasion." (PMID 34991274, 2018). "In addition, downregulation of miR-98 promoted the migration and invasion in esophageal squamous cell carcinoma (ESCC) through targeting EZH2." (PMID 29970191, 2018). "Esophageal squamous cell carcinoma, which exhibits high expression of BMI1 and EZH2, showed poor OS and disease-free survival." (PMID 29415665, 2018). "In esophageal squamous cell carcinoma (ESCC), high EZH2 expression was significantly correlated with increased cell proliferation (p = 0.009) and lack of clinical complete response to CRT (p = 0.028)." (PMID 25159232, 2014). "Increased H19 expression promoted the epithelial–mesenchymal transition, growth, and invasion of ESCC (esophageal squamous cell carcinoma) and NPC by inhibiting E-cadherin expression and modulating the STAT3/EZH2/β-catenin pathway." (PMID 41020820, 2025). "It is noteworthy that, in esophageal squamous cell carcinoma (ESCC), XIST leads to increased levels of the enhancer of zeste homolog 2 (EZH2) by sequestering miR-101." (PMID 35804851, 2022).
esophageal squamous cell carcinoma (continued). "In esophageal squamous cell carcinoma (ESCC), high EZH2 expression was significantly correlated with lack of clinical complete response to CRT (p = 0.028) and poor disease-specific survival (p < 0.001)." (PMID 25159232, 2014).
Ewing sarcoma (33 papers, 2011 to 2025). A small round cell tumor that lacks morphologic, immunohistochemical, and electron microscopic evidence of neuroectodermal differentiation. "Three patients (including two with Ewing sarcoma and one with ependymoma) enrolled based on EZH2 mutations experienced tumor progression and discontinued treatment after two cycles of tazemetostat." (PMID 39984702, 2025). "EZH2 levels have also been shown to be associated with metastasis of pediatric rhabdomyosarcoma, Ewing sarcoma, and synovial sarcoma." (PMID 38886296, 2024). "The inhibition of EZH2 in Ewing sarcoma cells resulted in a loss of their ability to grow independently in vitro and their tumorigenic potential in vivo, highlighting EZH2 as a potential therapeutic target." (PMID 37894854, 2023). "Here, we test the specific recognition and lytical potential of allo-restricted CD8+ T cells against Ewing tumour (ET) associated antigens Enhancer of Zeste, Drosophila Homolog 2 (EZH2), and Chondromodulin-I (CHM1) identified through previous microarray analysis." (PMID 21407224, 2011). "Furthermore, direct induction of EZH2 by the EWS-FLI1 fusion protein in Ewing’s sarcoma suggests that translocation-associated chimeric proteins may also play a regulatory role." (PMID 23110793, 2012). "Our findings indicate a genome-wide gain of H3K27me3 in relevant genes from EWSR1::FLI1 pathways, supporting the important role of EZH2 in Ewing sarcoma tumorigenesis." (PMID 41085408, 2025). "used an EZH2 inhibitor to enhance GD2 expression on the surface of Ewing sarcoma cells and significantly inhibited tumor progression when combined with GD2-CAR-T cells for the treatment of Ewing sarcoma." (PMID 39916962, 2024). "As a direct downstream target of EWSR1-FLI1, EZH2 plays a critical role in preserving the stemness characteristics of Ewing sarcoma cells." (PMID 37894854, 2023). "EWS-FLI1, a fusion oncoprotein in Ewing’s sarcoma, can transcriptionally activate EZH2 expression, and upregulated EZH2 expression plays a vital role in tumor growth and endothelial/neuroectodermal differentiation." (PMID 36622753, 2023). "In summary, downstream of EWSR1-FLI1, EZH2 acts to hinder the differentiation of Ewing sarcoma cells and sustains their stem cell-like state, which contributes to oncogenic transformation and the progression of tumors." (PMID 37894854, 2023). "Further, in preclinical studies, EZH2 inhibition in Ewing sarcoma induces the expression of ganglioside G-D2, which is then targeted with gene-modified T cells, resulting in tumor regression." (PMID 35795673, 2022). "In a preclinical model of Ewing’s sarcomas, the inhibition of enhancer of zeste homolog 2 (EZH2) selectively upregulated GD2 expression in GD2-low or GD2-negative Ewing’s sarcoma cells." (PMID 34771608, 2021). "The blockade of EZH2 expression in Ewing sarcoma cell lines decreased overall H3K27me3 and increased histone H3-acetylation (H3K27ac)." (PMID 34198693, 2021). "To upregulate GD2 to homogenous expression levels in Ewing sarcoma we chose an alternative epigenetic inhibitor, against Enhancer of Zeste Homolog 2 (EZH2)." (PMID 32357417, 2020). "Ramaglia10 found that EZH2 was expressed with a different degree in 60% of 17 patients with Ewing sarcoma or RMS and it was significantly higher in patients presenting lymph node and/or distant metastases." (PMID 30120321, 2018). "The data set GSE68591-3078349 showed the expression level of EZH2 mRNA in LMS was significantly lower than Ewing’s sarcoma (p < 0.05)." (PMID 30120321, 2018). "The H3K27me3 modification is mediated by the polycomb repressive complex protein EZH2, which functions as a histone methyltransferase and as a pro-tumorigenic oncogene in Ewing sarcoma." (PMID 27528222, 2016). "High levels of EZH2 in Ewing sarcoma cells contribute to maintenance of the tumorigenic state and this is mediated, at least in part, by EZH2-mediated repression of cell differentiation." (PMID 27528222, 2016).
Ewing sarcoma (continued). "EZH2 is therefore believed to drive tumor cells into a more aggressive, embryonic stem-like state, as it is clearly exemplified by EZH2-overexpressing tumors with embryonic morphology like rhabdomyosarcoma or Ewing’s sarcoma." (PMID 23110793, 2012). "Specifically, EZH2 was found to upregulate genes directly responsible for neuroectodermal and endothelial differentiation in Ewing's sarcoma cells." (PMID 22523703, 2012). "Studying the influence of EZH2 downregulation on gene expression, Richter and colleagues found that EZH2 is responsible for the undifferentiated phenotype of Ewing's sarcoma by maintaining a stemness gene expression signature, inhibiting differentiation." (PMID 21609503, 2011). "Strikingly, EWS/FLI1 has been found to induce the expression of EZH2 by direct binding to its promoter in both Ewing's sarcoma cell lines and human MSCs." (PMID 21609503, 2011). "Moreover, suppression of EZH2 expression in Ewing sarcoma cell lines inhibited contact-independent growth, favored cell differentiation, and reduced tumor growth as well as metastatic dissemination in vivo." (PMID 34198693, 2021). "Thus, repression of CXCR4 expression in Ewing sarcoma is, at least in part, dependent on EZH2 and on the presence of the H3K27me3 modification at the gene promoter." (PMID 27528222, 2016). "However, given our current findings, it will be important to consider that use of EZH2 inhibitors as anti-cancer agents in Ewing sarcoma could have the on-target, but undesirable, effect of activating CXCR4." (PMID 27528222, 2016). "Expression of EZH2 and the RAR genes was either similar or lower in SS compared to other STS, except for RARβ, which showed higher levels in SS compared to Ewing sarcoma." (PMID 39550391, 2024). "In Ewing sarcoma, EWSR1-FLI1 binds to the EZH2 promoter, prompting the transcriptional upregulation of EZH2." (PMID 37894854, 2023). "EZH2 directly binds to promotor regions of ST8SIA1, and inhibition of EZH2 enhances the expression of this gene in Ewing sarcoma cells." (PMID 36313564, 2022). "An earlier report showed that EZH2 helps EWS-FLI1 to drive tumor growth and metastasis in Ewing sarcoma." (PMID 35455947, 2022). "In cell lines derived from Ewing sarcoma, endogenous EWS/FLI1 can bound to the promoter region of EZH2 and regulate its expression in a dose-dependent manner." (PMID 34198693, 2021). "In preclinical studies, inhibitors of EZH2 reliably, reversibly, and selectively upregulated GD2 surface expression in GD2-low or GD2-negative Ewing sarcoma cells to levels inducing effective antigen-specific activation of CAR T cells." (PMID 32357417, 2020). "EWS-FLI1 knockdown based studies and transcriptional profiling data of various Ewing’s sarcoma cell lines have shown that gene like NR0B1, NKX2.2, EZH2, GLI1 are up regulated by EWS-FLI1." (PMID 23145994, 2012). "It is noteworthy that, in Ewing's sarcoma cells, HDAC inhibitor treatment in vitro induces downregulation of EZH2, as more recently confirmed in glioma, gallbladder carcinoma and acute myeloid leukemia." (PMID 21609503, 2011). "Indeed, EZH2 is a well-known directly activated target of EWSR1::FLI1 that blocks neuroectodermal and endothelial differentiation in Ewing sarcoma." (PMID 41085408, 2025). "In conclusion, in contrast to Ewing sarcoma, pretreatment with EZH2 inhibitors is not effective to overcome low and heterogeneous GD2 surface expression in OS." (PMID 33811471, 2021). "Next, expression levels of eight EWS-FLI1 associated target genes (GLI1, NEX2.2, CyclinD, c-MYC, NR01B, IGF1R, EZH2, and CD99) which were known to be upregulated, and three genes (FOXO1, IGFBP3, and LOX) known to be down regulated in Ewing’s sarcoma was assessed." (PMID 28775288, 2017). "The EWSR1-FLI-1 fusion protein pathognomonic for Ewing sarcoma (ES) binds the promoter of histone methyltransferase (HMT) enhancer of Zeste, Drosophila, Homolog 2 (EZH2) to promote expression in ES." (PMID 28654693, 2017).
Ewing sarcoma (continued). "Thus, using EZH2 inhibitors for sensitizing cancer cells to GD2‐targeted therapy may be a valuable option in Ewing sarcoma, but not in OS." (PMID 33811471, 2021). "Western blot analyses of SS18-SSX, PRAME, and EZH2 showed PRAME expression in translocation positive SS (TP-SS) and in other STS cells, including the RD-ES Ewing sarcoma cell line, while the SW982 translocation negative (TN-SS) cells had no detectable expression." (PMID 39550391, 2024).
myeloproliferative neoplasm (33 papers, 2011 to 2025). A clonal hematopoietic stem cell disorder, characterized by proliferation in the bone marrow of one or more of the myeloid (i.e., granulocytic, erythroid, megakaryocytic, and mast cell) lineages. "In EZH2-mutated patients with myelodysplastic or myeloproliferative neoplasms, the most common co-mutations were in ASXL1 (100%), NRAS, RUNX1, and STAG2 (29% each)." (PMID 33845873, 2021). "While mice harboring NRasG12D alone developed indolent myeloproliferative neoplasms (MPNs) and EZH2 deletion alone had minimal effects on hematopoiesis, combined NRasG12D and EZH2 mutations cooperatively induced MPN progression to lethal AML11." (PMID 34732703, 2021). "In NRASG12D-mutant myeloproliferative neoplasms, EZH2 deficiency is associated with elevated expression of BCAT1." (PMID 34109280, 2021). "However, EZH2 can also act as a tumor suppressor, with loss-of-function mutations identified in a subset of myelodisplastic syndromes, myeloproliferative neoplasms and T cell acute lymphoblastic leukemias." (PMID 27449082, 2016). "EZH2 mutations in MDS and myeloproliferative neoplasms are typically loss-of-function mutations, correlating with poorer outcomes." (PMID 39355256, 2024). "EZH2 is the catalyst to H3 methylation at lysine 27, and EZH2 mutations are common in patients with MDS and myeloproliferative neoplasms (12%)." (PMID 34575830, 2021). "Critically, inhibition of either BCAT1 or mTOR is selectively detrimental to EZH2-null cells and prevents the transition of myeloproliferative neoplasms to leukemia." (PMID 34109280, 2021). "For instance, EZH2 mutations occur in follicular lymphoma (FL), germinal center B-cell like (GCB) DLBCLs, MDS, myeloproliferative neoplasms (MPN), and juvenile myelomonocytic leukemia (JMML)." (PMID 34204821, 2021). "We next applied TARGET-seq to analyze 458 HSPCs in samples from five patients with myeloproliferative neoplasms (MPN); the samples carried different combinations of JAK2V617F, EZH2, and TET2 mutations." (PMID 30765193, 2019). "Mutations of EZH2, TET2, IDH1/2, and DNMT3A involved in epigenetic regulation are frequently observed in adult AML, MDS, and myeloproliferative disease (MPD)." (PMID 25914884, 2015). "The role of EZH2 in CML remains unclear, and unlike other myeloid malignancies, inactivating mutations of EZH2 are rare in CML, although the upregulation of EZH2 can result in a form of myeloproliferative disease." (PMID 37762109, 2023). "A higher expression level of Ezh2 induces myeloproliferative disease in mice." (PMID 34944812, 2021). "Loss-of-function mutations in EZH2 are frequently found in patients with MDS and myeloproliferative neoplasms (MPN)." (PMID 33374737, 2020). "Both monoallelic and biallelic mutations (missense mutation, frameshift mutation, premature stop codons and splicesomal mutations) of EZH2 have been identified in around 23% of various subtypes of MDS, myeloproliferative neoplasms (MPN), and MDS-MPN overlap disorders." (PMID 33003334, 2020). "Specifically, loss of EZH2 promotes AML initiation, reflected in low-frequency loss-of-function mutations in myeloid neoplasms, and the observed acceleration of AML transformation from pre-malignant myeloproliferative neoplasms (MPN)." (PMID 31572684, 2019).